NUP205 (nucleoporin 205)
Description:
Plays a role in the nuclear pore complex (NPC) assembly and/or maintenance. May anchor NUP62 and other nucleoporins, but not NUP153 and TPR, to the NPC. In association with TMEM209, may be involved in nuclear transport of various nuclear proteins in addition to MYC.
Synonyms: C7orf14; KIAA0225; NPHS13
Tractability: Antibody: UniProt places it where antibodies can reach, with high confidence. PROTAC: ubiquitination databases record sites on it; its protein half-life has been measured.
Gene: Protein-coding gene on chromosome 7 (135,557,726 to 135,648,757, forward strand). Ensembl gene ENSG00000155561.
Subcellular location: Nucleus membrane; Nucleus, nuclear pore complex
Pathways (Reactome):
Disease: Defective TPR may confer susceptibility towards thyroid papillary carcinoma (TPC); HCMV Early Events; HCMV Late Events; NEP/NS2 Interacts with the Cellular Export Machinery; NS1 Mediated Effects on Host Pathways; Nuclear import of Rev protein; Rev-mediated nuclear export of HIV RNA; SARS-CoV-2 activates/modulates innate and adaptive immune responses; Transport of Ribonucleoproteins into the Host Nucleus; Viral Messenger RNA Synthesis; Vpr-mediated nuclear import of PICs
Metabolism of RNA: Transport of Mature mRNA Derived from an Intronless Transcript; Transport of Mature mRNA derived from an Intron-Containing Transcript; Transport of the SLBP Dependant Mature mRNA; Transport of the SLBP independent Mature mRNA; snRNP Assembly; tRNA processing in the nucleus
Metabolism of proteins: SUMOylation of DNA damage response and repair proteins; SUMOylation of DNA replication proteins; SUMOylation of RNA binding proteins; SUMOylation of SUMOylation proteins; SUMOylation of chromatin organization proteins; SUMOylation of ubiquitinylation proteins
Metabolism: IP3 and IP4 transport between cytosol and nucleus; IP6 and IP7 transport between cytosol and nucleus; IPs transport between nucleus and cytosol; Regulation of Glucokinase by Glucokinase Regulatory Protein
Cell Cycle: Nuclear Pore Complex (NPC) Disassembly; Postmitotic nuclear pore complex (NPC) reformation
Cellular responses to stimuli: Regulation of HSF1-mediated heat shock response
Immune System: ISG15 antiviral mechanism
Gene Ontology:
Molecular function: protein binding; structural constituent of nuclear pore
Biological process: nuclear pore complex assembly; nuclear pore organization; nucleocytoplasmic transport
Cellular component: membrane; nuclear envelope; nuclear membrane; nuclear periphery; nuclear pore; cytosol; nuclear pore inner ring
Genetic constraint (gnomAD): Loss-of-function variants: 58 observed, 196.95 expected, observed/expected ratio (o/e) 0.29, 90% interval 0.24 to 0.37. The upper end of that interval is the gene's LOEUF score, 0.37, which puts it in group 1 of 6, group 1 being the genes least tolerant of losing a copy. Missense variants: 1,800 observed, 2,097.4 expected, observed/expected ratio (o/e) 0.86, 90% interval 0.82 to 0.89. Synonymous variants: 713 observed, 756.02 expected, observed/expected ratio (o/e) 0.94, 90% interval 0.89 to 1.
Gene-disease validity (ClinGen):
ClinGen rates the evidence that NUP205 causes each of these diseases.
nephrotic syndrome, type 13 (autosomal recessive): Limited.
Homologues: Orthologues: chimpanzee NUP205 (99% identical), macaque NUP205 (99% identical), pig NUP205 (97% identical), dog NUP205 (97% identical), rabbit NUP205 (96% identical), rat Nup205 (94% identical), mouse Nup205 (93% identical), guinea pig NUP205 (90% identical), tropical clawed frog nup205 (78% identical), zebrafish nup205 (70% identical), Drosophila melanogaster Nup205 (31% identical), Caenorhabditis elegans npp-3 (19% identical).
Diseases named in the same sentence as NUP205 in open-access papers:
NUP205 is named in the same sentence as 32 diseases in open-access papers, as found by Europe PMC text mining. Sharing a sentence is not in itself a finding about the gene and the disease. The quoted sentences say what the papers report.
lung carcinoma (4 papers, 2016 to 2024). "TMEM209 and NUP205 protein interactions, stabilizing NUP205 and increasing the level of c-Myc in the nucleus, are critical drivers of lung cancer proliferation." (PMID 34299277, 2021). "In lung cancer cell lines it was shown that through TMEM209 stabilization of NUP205, protein levels of MYC were increased and promoted cell growth." (PMID 27115612, 2016). "Interestingly, previous study indicated that TMEM209 stabilized NUP205 in the protein level in lung cancer cells; however, a detailed understanding of its mechanism was lacking." (PMID 39414762, 2024). "Furthermore, NUP205 has been shown to promote cell growth in lung cancer through its interaction with transmembrane protein 209 (TMEM209), which stabilizes NUP205 and regulates c-Myc nuclear entry." (PMID 39080077, 2024).
nephrotic syndrome (3 papers, 2021 to 2022). A collection of symptoms that include severe edema, proteinuria, and hypoalbuminemia; it is indicative of renal dysfunction. "The role of NUP205 in bone is currently unclear, but a previous study demonstrated that inactivating missense mutations in NUP205 are associated with steroid-resistant nephrotic syndrome." (PMID 33988819, 2021). "Mutations in NUP205 are associated with steroid-resistant nephrotic syndrome." (PMID 34020649, 2021).
amyotrophic lateral sclerosis (2 papers, 2021 to 2022). Amyotrophic lateral sclerosis (ALS) is a neurodegenerative disease characterized by progressive muscular paralysis reflecting degeneration of motor neurons in the primary motor cortex, corticospinal tracts, brainstem and spinal cord. "Moreover, several potential disease-causing genes were detected and markedly enriched in the pathways of neurodegeneration (including WNT16, RYR3 and RYR1 genes) and amyotrophic lateral sclerosis (ALS, including NUP205, CAPN2, and NUP214 genes)." (PMID 35355568, 2022).
bladder cancer (2 papers, 2020 to 2022). "Using a Cox proportional regression model, we established that a 4-mRNA signature (NUP205, NUPL2, PFKFB1 and PKM) was significantly associated with prognosis in bladder cancer patients." (PMID 32467671, 2020). "Another four-gene glycolytic signature (NUP205, NUPL2, PFKFB1, and PKM) showed excellent performance in predicting the OS of bladder cancer patients." (PMID 35109912, 2022).
congenital heart disease (2 papers, 2023 to 2024). A heart disease that is present at birth. "For example, genetic variants of Nup205 and Nup188 were found in the patients with congenital heart disease and situs inversus totalis or heterotaxy." (PMID 39720592, 2024). "Genetic variants of Nup205 and Nup188 have been identified in patients with congenital heart disease and situs inversus totalis or heterotaxy, a prevalent human ciliopathy." (PMID 37908226, 2023).
hepatocellular carcinoma (2 papers, 2023). A malignant tumor that arises from hepatocytes. "For example, high NUP205 expression leads to poor prognosis in patients with hepatocellular carcinoma." (PMID 37284202, 2023). "The qRT-PCR results showed that TOMM40L, SNRPA, ILF3, CPSF6, and NUP205 were remarkably highly expressed in hepatocellular carcinoma." (PMID 37745063, 2023). "For example, the high expression of NUP205 increases the proliferation ability of hepatocellular carcinoma cells, leading to poor prognosis in these patients." (PMID 37284202, 2023).
retinoblastoma (2 papers, 2016 to 2023). A malignant tumor that originates in the nuclear layer of the retina. "For chromosome 7q gains, out of 10 proposed candidates based on primary retinoblastoma samples, only NUP205 is included in a focal gain observed in cell line RB191." (PMID 27115612, 2016). "Besides the well-established driver genes RB1 (13q-loss) and MYCN (2p-gain) we identified CRB1 and NEK7 (1q-gain), SOX4 (6p-gain) and NUP205 (7q-gain) as novel retinoblastoma driver candidates." (PMID 27115612, 2016).
acute myeloid leukemia (1 paper, 2020). Acute myeloid leukemia (AML) is a group of neoplasms arising from precursor cells committed to the myeloid cell-line differentiation. "Overexpression of SNHG1 facilitates the proliferation via miR-488-5p/NUP205 pathway in acute myeloid leukemia cells." (PMID 32536864, 2020).
anaplastic astrocytoma (1 paper, 2023). "Third, analysis of the histological types of LGG from the TCGA RNA-seq database showed that NUP205 expression is highest in anaplastic astrocytoma (AA) and lowest in astrocytoma (A)." (PMID 37284202, 2023).
aortic valve stenosis (1 paper, 2022). Aortic valve stenosis (AVS) is a condition characterized by narrowing of the heart's aortic valve opening. "The finding indicates the mutations TTN, NUP205, and NCOR2 can enhance the severity of aortic valve stenosis, a consequence of BAV." (PMID 36071494, 2022).
focal segmental glomerulosclerosis (1 paper, 2024). A renal disorder characterized by sclerotic lesions in the glomeruli. "For example, focal segmental glomerulosclerosis (FSGS), which is caused by deficient podocytes, is now believed to be associated with mutations in Nup93 and Nup205." (PMID 39768219, 2024).
glioma (1 paper, 2023). A benign or malignant brain and spinal cord tumor that arises from glial cells (astrocytes, oligodendrocytes, ependymal cells). "In addition, HDAC11, which was negatively correlated with the expression of NUP205, was found to have low expression in glioma tissue and was associated with a better prognosis in glioma patients." (PMID 37284202, 2023). "In our study, the NCAPG2 and BAZ1B genes were positively related to NUP205 and have been reported as oncogenes for glioma." (PMID 37284202, 2023). "We found that NUP205 expression decreased in glioma cells after treatment with promethylating drugs compared to untreated LGG cells." (PMID 37284202, 2023). "Our results suggest that many genes that positively correlate with NUP205 play a role in the carcinogenesis of glioma." (PMID 37284202, 2023). "The RT-qPCR results showed that NUP205 expression significantly decreased in glioma cells cultured with SAM." (PMID 37284202, 2023). "The expression of NUP205 in these glioma cells was higher than that in normal human astrocytes." (PMID 37284202, 2023). "By reviewing previous studies, we found that CASP2, NCAPG2, BAZ1B, and ZNF800, the genes most positively related to NUP205, were reported as carcinogenic genes in cancer, especially CASP2, NCAPG2, and BAZ1B, which were found to be carcinogenic genes in glioma." (PMID 37284202, 2023). "First, we found that the mRNA and protein expression of NUP205 in WHO Grade III gliomas was significantly higher than that in WHO Grade II gliomas, and that the prognosis of glioma patients worsens with the improvement of WHO Grade." (PMID 37284202, 2023).
HIV-1 infection (1 paper, 2018). The type species of lentivirus and the etiologic agent of acquired immunodeficiency syndrome (AIDS). "In fact, several Nup depletions (NUP205, NUP62, NUP54, and NUPL1) had larger effects on HIV-1 infection in non-dividing as compared to dividing HOS cells." (PMID 30084827, 2018). "Moreover, some Nup depletions (SEH1, NUP85, NUP160, SEC13, NUP98, NUP107, ELYS/ACHTF1, NUP93, NUP205, NUP88, and NUP214) that reduced both HIV-1 infection and MX2 activity in dividing HeLa cells, affected MX2 activity but not HIV-1 infection in non-dividing HeLa cells." (PMID 30084827, 2018).
liver fibrosis (1 paper, 2022). "In addition, we found that other CHB-related loci, such as HSD17b8, ITPR3, NUP205, RING1, and SKIV2l, were upregulated or downregulated in different ways in the groups with different degrees of liver fibrosis." (PMID 36406135, 2022).
malaria (1 paper, 2021). Malaria is a serious and sometimes fatal disease caused by a parasite that commonly infects a certain type of mosquito which feeds on humans. "To determine whether NAB2 localizes to the inside of the nuclear membrane in malaria parasites, we generated a NAB2::mCherry strain expressing NUP205 fused to green fluorescent protein (GFP)." (PMID 34604117, 2021).
nasopharyngeal carcinoma (1 paper, 2023). A carcinoma arising from the nasopharyngeal epithelium. "The expression of NUP205 in nasopharyngeal carcinoma tumor tissue was significantly upregulated compared with that in adjacent tissue, which was an important factor leading to the proliferation of nasopharyngeal carcinoma cells." (PMID 37284202, 2023).
papillary thyroid carcinoma (1 paper, 2023). "For example, LncRNA HOTAIR can upregulate the expression of NUP205 to increase the growth, migration, and invasion of papillary thyroid carcinoma cells via absorbing the role of miR-488-5p." (PMID 37284202, 2023).
viral infections (1 paper, 2021).
tumor (4 papers, 2016 to 2026). "Nucleoporin 205 (NUP205)—a main component of NPC—plays a key regulatory role in tumor cell proliferation; however, few reports document its effect on the pathological progression of lower-grade glioma (LGG)." (PMID 37284202, 2023). "In addition, the results of western blotting showed that the protein expression of NUP205 in the WHO Grade III tumor tissue was significantly higher than that of WHO Grade II tissue." (PMID 37284202, 2023). "Only NUP205 showed a significant association (FDR-adjusted p-value 2.62E-5) between copy numbers and expression and was also identified as a candidate in the primary tumor data set." (PMID 27115612, 2016). "Therefore, we conducted an integrated analysis using 906 samples from multiple public databases to explore the effects of NUP205 on the prognosis, clinicopathological characteristics, regulatory mechanism, and tumor immune microenvironment (TIME) formation in LGG." (PMID 37284202, 2023). "In addition, HOTAIR baits miR-488-5p, boosting nucleoporin 205 (NUP205) and the apoptotic protein BCL-2, thereby aiding tumor growth." (PMID 41489907, 2026). "Interestingly, AVPI1, FKBP8, and ALDH2, which were most negatively correlated with NUP205 in LGG, were all reported to be tumor suppressor genes in cancer." (PMID 37284202, 2023).
cancer (3 papers, 2020 to 2025). A tumor composed of atypical neoplastic, often pleomorphic cells that invade other tissues. "The association between the clinical progression of cancer and the high expression of pathogenic genes prompted us to report the expression of NUP205 in patients with LGG." (PMID 37284202, 2023). "Existing studies have all reported that NUP205 is an oncogene in several cancers, leading us to believe that NUP205 may also be a pathogenic gene in LGG." (PMID 37284202, 2023). "Thus, many scientists have studied the role of abnormal NUP205 in cancers and found that NUP205 is also closely related to tumorigenesis." (PMID 37284202, 2023). "However, using RT-qPCR for further validation, we found that only NUP205 and PKM were upregulated in cancer tissues, and the expression of PFKFB1 in cancer tissues was lower than that in adjacent normal tissues." (PMID 32467671, 2020).
infection (2 papers, 2018 to 2020). The state of being infected such as from the introduction of a foreign agent such as serum, vaccine, antigenic substance or organism. "Moreover, NUP205 depletion caused HIV-1A92E infection to become CsA-dependent in HT1080 cells." (PMID 30084827, 2018). "FIV infectivity and MX2 resistance were also unaffected by most Nup depletions in HT1080 cells, but a small number of knockdowns (NUP93, NUP205, NUP160) were significantly deleterious to FIV infection in HOS cells." (PMID 30084827, 2018). "The CsA dependence of HIV-1A92E infection in HeLa cells was exaggerated by some Nup knockdowns (e.g. NUP93, NUP205, NUP54, NUP153) while other knockdowns reduced or eliminated the enhancing effects of CsA (e.g. NUP98, NUP107, NUP155)." (PMID 30084827, 2018). "Infection by HIV-1N57S was strongly inhibited by CsA in HT1080 cells and Nup depletions partly (e.g. NUP62, NUP54, NUPL1) or nearly completely (e.g. NUP155, NUP205) abolished this CsA sensitivity." (PMID 30084827, 2018). "Additionally, the ability of MX2 to rescue HIV-1N57S infection from inhibition by CsA in HT1080 cells was reduced by NUP93 and NUP205 depletion." (PMID 30084827, 2018).
retinal disorder (1 paper, 2020). Any disease or disorder of the retina. "This contradicts the presumption that most retinal disorders in the Phenopolis dataset are rare Mendelian disorders, therefore we believe “NUP205 –Abnormal electroretinogram—dominant” is a false positive." (PMID 32271766, 2020).
NUP205 also shares sentences with these, for which no sentence is quoted: Situs inversus totalis (2 papers); astrocytoma (1); autism (1); ciliopathy (1); infantile bilateral striatal necrosis (1); Intellectual disability (1); leukemia (1); melanoma (1); ovarian yolk sac tumor (1); steroid-resistant nephrotic syndrome (1).